HIF1A (hypoxia inducible factor 1 subunit alpha)
Diseases named in the same sentence as HIF1A in open-access papers (continued):
Sharing a sentence is not in itself a finding about the gene and the disease.
breast cancer (continued). "In summary, this study revealed a novel mechanism that NCOA1 potentiates breast cancer angiogenesis through upregulating HIF1α and AP-1-mediated VEGFa expression, which reinforces the rational of targeting NCOA1 in controlling breast cancer progression and metastasis." (PMID 26287601, 2015). "Furthermore, overexpression of 12-LOX in prostate or breast cancer cells stimulates growth in tumor xenograft models, and tumor angiogenesis, where 12-LOX overexpression regulates HIF1α." (PMID 26037302, 2015). "We engineered triple (estrogen receptor/progesterone receptor/HER2/neu) negative, invasive MDA-MB-231 and SUM149 human breast cancer cells to silence the expression of HIF-1α, HIF-2α or both isoforms of HIF-α." (PMID 26305551, 2015). "Our results demonstrate that BRMS1 attenuates TGF-β1-induced breast cancer cell invasion through inhibition of NF-κB and subsequent reduction of HIF-1α expression required for Snail and TWIST1 expression, uncovers a new mechanism through which BRMS1 suppresses breast cancer progression." (PMID 26520789, 2015). "Expression of MIF often correlates with the state of hypoxia, although MIF expression is not dependent on hypoxia or HIF1α in MCF-7 breast cancer cells." (PMID 26352431, 2015). "Hypoxia induced the binding of HIF-1α, but not HIF-1β, to the CTGF promoter in NTC cells, but not in TAZ knockdown cells, demonstrating that TAZ recruits HIF-1α to the CTGF proximal promoter in hypoxic breast cancer cells." (PMID 26059435, 2015). "Moreover, MCF10A-ERBB2 cells expressing HIF-1α RNAi abrogated DUSP2 downregulation under hypoxia, thus regulation of DUSP2 by hypoxia in breast cancer cells is HIF-1α-dependent." (PMID 25596742, 2015). "HIF-1α also recruits histone demethylases including JMJD2C, which demethylates trimethylated lysine 9 of histone H3 and enhances HIF-1 binding to HREs to activate transcription of HIF-1 target genes and drive breast cancer metastasis." (PMID 26059435, 2015). "Therefore, we suggest that the HIF-1α hyperactivation is a critical marker of increased aerobic glycolysis in accordance with tamoxifen resistance and thus restoration of aerobic glycolysis may be novel therapeutic target for treatment of tamoxifen-resistant breast cancer." (PMID 26158266, 2015). "We previously demonstrated that HIF-1α and TAZ cooperate to induce the breast cancer stem cell phenotype but further studies are required to determine the specific target genes and mechanisms of transcriptional activation and co-activation that mediate this effect." (PMID 26059435, 2015). "A proportion of TNBC express HIF-1α but not in a significantly different manner from other breast cancer subtypes." (PMID 26046764, 2015). "Besides exosomes, hypoxia significantly enhanced the microvesicles biogenesis in a HIF1α- and RAB22A GTPase-dependent manner, and promoted the formation of focal adhesions, invasiveness and metastasis in naïve breast cancer cells." (PMID 26087400, 2015). "Given that BRMS1 inhibits Snail and TWIST1 expression and that hypoxic condition induces Snail and TWIST1 expression in breast cancer cells, we hypothesized that BRMS1 inhibits HIF-1α expression." (PMID 26520789, 2015). "For breast cancer, XBP1 promoted triple-negative breast cancer by regulating HIF-1α pathway." (PMID 26633383, 2015). "This suggests that the combined detection of HIF-1α, OGT, and OGA in clinical samples may be useful as potential breast cancer biomarkers." (PMID 25426101, 2014). "Therefore, the relationships between genotypes of SNP 1772 C > T of HIF-1α gene and the clinicopathologic characteristics, the immunostaining expression levels of HIF-1α and VEGF, and clinical outcomes of breast cancer are also addressed in this study." (PMID 25302049, 2014). "Other study found that the HIF-1α overexpressed in immunostaining measurement for invasive breast cancer in the absence of 1772 C > T transition of HIF-1α gene." (PMID 25302049, 2014).
breast cancer (continued). "Recent experiments measured the in vivo longitudinal data of these four parameters with tumor development and the corresponding presence and absence of tumor macrophage HIF-1α or HIF-2α in a mouse model of breast cancer." (PMID 25295611, 2014). "Inherent upregulation of HIF-1α protein expression under nonhypoxic conditions is another novel finding in AI-resistant breast cancer." (PMID 24472707, 2014). "Although in this report we do not study growth and metastasis of breast cancer cells, the approach to understand the effect of estrogens on the processes is focused on the regulation of HIF-1α expression." (PMID 23549681, 2013). "The present study tests the hypothesis that EGCG can inhibit the activation of HIF-1α and NFκB, and VEGF expression, thereby suppressing tumor angiogenesis and breast cancer progression." (PMID 23638734, 2013). "A study on breast cancer cells where HER2 signalling specifically induced HIF-1α protein expression without affecting HIF-1α mRNA showed the response was dependent upon activation of the PI3K/Akt/FRAP thus increasing rate of protein synthesis." (PMID 24180698, 2013). "Previously HER2 signaling in non-hypoxic MCF-7 breast cancer cells has been shown not only to affect HIF1α stability but also to increase dramatically the rate of HIF1α protein synthesis." (PMID 23342109, 2013). "More specifically, it has been shown that HIF-1α may induce an enhanced expression of lysyl oxidase (LOX), lysyl oxidase-like 2 (LOXL2) and LOXL4 in hypoxic breast cancer cells within primary breast tumour." (PMID 23301832, 2013). "Additionally, the differential expression of prolidase in two breast cancer cell lines MCF-7 and MDA-MB-231 showed prolidase-dependent differences in HIF-1α levels." (PMID 23549681, 2013). "miR-20b modulates VEGF expression by targeting HIF-1α and STAT3 in MCF-7 breast cancer cells." (PMID 24130753, 2013). "We used VEGF ELISA kit and HIF-1α and NFκB activation (Motif Binding) assays to determine whether EGCG could suppress HIF-1α and NFκB activation and VEGF expression in cultured mouse breast cancer (E0771) cells." (PMID 23638734, 2013). "Considering that hypoxia regulates HIF-1α-dependent expression of both GPER and VEGF in different model systems, in the present study we aimed to evaluate the potential involvement of GPER in the expression and function of VEGF in CAFs and breast cancer cells." (PMID 23947803, 2013). "Hypoxia, a key signal for the induction of angiogenesis, increased the expression of hypoxia-inducible factor (HIF-1α), which is overexpressed in poorly differentiated breast cancer compared to well-differentiated carcinoma and nonmalignant breast tissue." (PMID 24202338, 2013). "Here, we provide the first insights regarding the molecular mechanisms of NMBR regulation in breast cancer cells by demonstrating that hypoxia increased NMB-R expression in human cancer cells and that HIF-1α directly bound to and transactivated the NMBR promoter in response to hypoxia." (PMID 24349381, 2013). "YC-1 did not promote degradation of HIF-1α in T47-D breast cancer cells under the conditions employed, indicating that PR loss did not occur as a result of a generalized cytotoxic effect of YC-1." (PMID 23123638, 2013). "Over-expression of HIF-1α is a common feature of malignant cells and links to poor prognosis in both lymph-node positive and lymph-node negative breast carcinoma." (PMID 23496980, 2013). "It is also important to point out that necrosis was shown recently to be a typical representative of basal-like breast cancer, and that in breast cancer patients whose tumors overexpress HER2, higher levels of activated AKT2 and the hypoxic-induced protein; HIF-1α were observed." (PMID 22511931, 2012). "The association of HIF-1α and PROM1 expression in ER- breast cancers is not surprising, given that hypoxia is a potent stimulator of ERα degradation." (PMID 22225988, 2012).
breast cancer (continued). "In contrast to observations from either PyMT model system in which Hif1a was deleted, short hairpin RNA-mediated knockdown of HIF1A in MDA-MB-231 breast cancer cells does not significantly change cell number at either normoxia or hypoxia (1% O2)." (PMID 22225988, 2012). "HIF1-α has also been shown to induce epithelial-mesenchymal transition (EMT), which has recently been shown to be able to generate cells with stem cell properties in breast cancer." (PMID 23185379, 2012). "Reduced expression of CXCR4 in metastatic lesions as compared to corresponding primary tumors has been reported in breast carcinoma, and hypothesized to be due to CXCL12-induced internalization and degradation and/or lower microenvironmental HIF-1α levels." (PMID 23249693, 2012). "Given the role of HIF-1α in cancer progression and its activation by receptor tyrosine kinases (RTKs), the current study investigates the role of oestrogen in stimulating HIF-1α expression in breast cancer cells." (PMID 21897387, 2011). "In addition, LS081 markedly decreased HIF-1α and -2α levels in DU-145 prostate cancer cell line and the MDA-MB-231 breast cancer cell lines, stimulated ROS production, and decreased clonogenicity." (PMID 21453502, 2011). "In this study, we reported that hypoxia could induce HIF-1α and VEGF expression accompanied by Rac1 activation in MCF-7 breast cancer cells." (PMID 21980400, 2011). "Reduced expression of miR-148a in breast cancer cells leads to the elevation of ERBB3 expression to activate AKT and ERK1/2 signaling pathways, which may in turn increase p70S6K1 activation and HIF-1α expression." (PMID 23554686, 2011). "On the other hand, the expression of HIF-1α was correlated with the presence of ObR in primary breast cancer regardless of preoperative treatment." (PMID 20569445, 2010). "We analyzed interactions between HIF-1α and TGF-β pathways in MDA-MB-231 breast cancer cells." (PMID 19727403, 2009). "Next, we tested whether combined systemic inhibition of HIF-1α with 2ME2 and TGF-β with a TβRI kinase inhibitor SD-208 provided additional therapeutic benefit in a therapeutic model of breast cancer bone metastasis." (PMID 19727403, 2009). "Since HIF-1α is frequently expressed in breast carcinomas, DNA methylation at the promoter regions of the SDHA, SDHB, SDHC and SDHD and FH genes was evaluated as a possible mechanism in silencing of SDH and FH expression in breast carcinomas." (PMID 19778456, 2009). "An immunohistochemical analysis of human breast cancers revealed that lack of Akt1 phosphorylation correlates with low HIF-1α levels." (PMID 19384426, 2007). "To better understand the regulation of HIF-1α in breast carcinoma, we have examined the expression of FIH-1 in a large characterized series of breast carcinomas and have correlated this with standard clinicopathological parameters and various markers of hypoxia." (PMID 18096060, 2007). "Overall, while multiple phytochemicals exhibit consistent anti-HIF-1α effects in vitro and in vivo, the absence of well-designed clinical trials directly measuring HIF-1α activity in breast cancer tumors precludes definitive conclusions regarding their therapeutic efficacy." (PMID 41614951, 2026). "Indeed, USP9X overexpression increased HIF-2α levels in a dose-dependent manner, without affecting the HIF-1α levels which has been reported as a USP9X substrate in breast cancer." (PMID 40246814, 2025). "In addition, curcumin inhibited HIF-1α and HIF-2α expression in breast cancer stem cells." (PMID 39859345, 2025). "Nimbolide, another neem limonoid was demonstrated to inhibit angiogenesis in breast cancer cells as well as in a xenografted nude mouse model of breast cancer by AR inhibition with the consequent abrogation of the insulin-like growth factor-1 (IGF-1)/PI3K/Akt and HIF-1α/VEGF signaling." (PMID 39055885, 2024).
breast cancer (continued). "HIF-1α is regulated by a complex network and drives the development of breast cancer through glycolysis, metastasis, angiogenesis, breast cancer stem cells enrichment and activation, and immune escape, indicating that targeting HIF-1α is of great significance for the treatment of breast cancer." (PMID 38236337, 2024). "The results showed that the mRNA level of HIF-1α did not change significantly between breast cancer cell groups, indicating that the regulation of HIF-1α by PDK1 may be transcriptionally independent." (PMID 38560503, 2024). "In breast cancer, HIF-1α and the G protein-coupled estrogen receptor (GPER) signaling pathway stimulate the expression of VEGF in CAFs, while GPER in breast cancer CAFs induces interleukin-1β (IL-1β) to express interleukin-1 receptor 1 (IL1R1) in breast cancer cells." (PMID 39192979, 2024). "Additional treatment in the HepG2 liver cancer cell line and MCF7 breast cancer cells established the combination of MET and SVA interfered with the ET-1-induced nuclear localisation of HIF-1α, along with PHD2 upregulation, resulting in increased degradation of HIF-1α, reducing angiogenesis." (PMID 38540124, 2024). "In a study for the treatment of paclitaxel-resistant breast cancer, it was observed that LINC00115 was strongly upregulated in paclitaxel-resistant BCSC, and that LINC00115 acted as an RNA linker recruiting the SETDB1/PLK3 complex to activate the HIF1α signaling pathway." (PMID 39372872, 2024). "Furthermore, HIF-1α phosphorylation at serine 451 was detected in wild-type breast cancer cells but not in PDK1 knockout breast cancer cells." (PMID 38560503, 2024). "However, differences in Hif1-α expression were not statistically significant between breast-cancer molecular subtypes." (PMID 38254864, 2024). "When MDA-MB-231 breast cancer cells were subjected to HIF-1α knockdown and thus lacked HSP90α secretion, the F-5 fragment could, as expected, restore the cell migration and invasion activities as effectively as full-length rHSP90α." (PMID 38994997, 2024). "In breast cancer (BC), the transcription of ITGB1 is activated by CDC42, FOXM1, HIF1α, and EZH2 to support the ability of BC cells to invade and spread." (PMID 38279122, 2024). "HIF-1α target pyruvate dehydrogenase kinase 1 (PDK1) is required for liver metastasis, and HIF-1α activity and PDK1 expression are elevated in liver metastasis of breast cancer patients, indicating that PDK1 is a key regulator of breast cancer metabolism and metastasis potential." (PMID 39588377, 2024). "It was experimentally demonstrated that HIF-1α under hypoxic conditions induced PDK1, a downstream target gene of HIF-1α, which promotes protein stability and transcriptional activity of HIF-1 α, forming a positive feedback loop that promotes breast cancer progression." (PMID 38560503, 2024). "The aim of this study was to investigate the inhibitory effect of miR-561-3p on ZEB1, HIF1A, and MYC expression as oncogenes that have the most impact on PD-L1 overexpression and cellular processes such as proliferation, apoptosis, and cell cycle in breast cancer (BC) cell lines." (PMID 38462658, 2024). "Hypoxia inducible factor 1 subunit alpha (HIF1A) and the lactate transporter solute carrier family 16 member 1(SLC16A1) also regulate aerobic glycolysis in cancer metabolism, whose high expressions are correlated with poor clinical outcomes in breast cancer patients." (PMID 37180167, 2023). "The aim of this study was to complement information from the immunohistochemical expression of endogenous markers of hypoxia (HIF-1α, CAIX) and vascularity (CD31) with imaging parameters of hypoxia and vascular function from simultaneous [18F]-FMISO-PET/MRI in treatment-naïve ER + breast cancer." (PMID 37166494, 2023).
breast cancer (continued). "It has been reported that Pentamidine suppresses the expression of hypoxia-inducible factor 1 alpha (HIF-1a) which correlates with increased vascularity, resistance to chemotherapy and radiotherapy, and poor prognosis in DU145 prostate and MDA-MB-231 breast cancer cell lines." (PMID 36434592, 2022). "In long-term adriamycin-treated breast cancer cells, TRPC5-mediated Ca2+ influx promoted HIF-1α translocation in the nucleus and therefore the downstream transcription of HIF-1α-regulated VEGF expression, highlighting its contribution to promoting breast cancer angiogenesis." (PMID 35806388, 2022). "Hypoxia-inducible factor 1-alpha (HIF1A) is the main transcriptional regulator of the adaptive response to hypoxia, which is related to metastasis of various tumor cells and poor prognosis of cancer patients, including sarcoma, advanced renal cell carcinoma (RCC), breast cancer, and NB." (PMID 35535346, 2022). "Targeting DLEU1, HIF-1α, or CKAP2 may thus benefit breast cancer treatment." (PMID 35853854, 2022). "Thus, the finding of heightened expression of HIF1α and HIF target genes in patients’ breast cancers with amplified KRAS can now be directly related to a perturbation of KRAS activity and likely that of more commonly mutated downstream elements in the KRAS pathway." (PMID 34294889, 2022). "In this study, we demonstrate the chemoresistance role of ATP-HIF-1α signaling both in vitro and in vivo by using conventionally cultured cell lines, 3D sphere formation assays, and BALB/c mouse models, suggesting the important role of HIF-1α in breast cancer therapy." (PMID 35236823, 2022). "HIF-1α accumulation under hypoxia might promote CLDN6 transcription, and increased CLDN6 would weaken HIF-1α protein stability and slow down hypoxia-induced breast cancer metastasis." (PMID 35847894, 2022). "HIF1A transforms normal stem cells into cancer stem cells by altering the niche components and functions of stem cells, leading to an increase in drug-resistant cancer stem cells in solid tumors, and HIF1A- and HIF2A-dependent AlkB homolog 5 expression induces the breast cancer stem cell phenotype." (PMID 35659268, 2022). "Because no clinical trials investigated HIF-1α inhibitors monotherapy in breast cancer yet, the efficacy of HIF-1α inhibitors monotherapy in breast cancer may not satisfactory either." (PMID 36003773, 2022). "Unexpectedly, similar to the well‐known hypoxia‐inducible protein, hypoxia‐inducible factor 1α (HIF1α), hypoxia could induce the expression of OVOL2 protein in MCF7, ZR75‐1 and MDA‐MB‐231 breast cancer cells, suggesting that OVOL2 expression is regulated at the protein level." (PMID 35896951, 2022). "They studied the role of DJ12 in breast cancer cell lines MDA-MB-468 and ZR-75, melanoma cell line MDA-MB-435, and pVHL mutant renal cancer cell lines RCC4 and 786-O and concluded that DJ12 not only blocks the binding of HIF-1α to HRE region of DNA but also interferes with its transactivation." (PMID 36014432, 2022). "Despite the relation between estrogen receptors and the hypoxia-inducible factor, based on the immunohistochemistry of the clinical samples of breast cancer, a higher frequency of HIF-1α was observed in the ER-α negative samples compared to the ER-α positive one." (PMID 36139678, 2022). "However, none of the HIF-1α inhibitors have been approved for the treatment of breast cancer patients in clinics due to insufficient effectiveness, toxicity, and lack of specificity." (PMID 36080483, 2022). "Additionally, it is clear that HIF-1α can bind with location 1 of the HK2 promoter where it is an upstream promoter site of HK2 and facilitates the transcription of HK2, which accelerates glycolysis and promotes breast cancer." (PMID 36230935, 2022).